ENSG00000300510 (novel protein similar to interferon induced transmembrane protein 3)
Gene: Protein-coding gene on chromosome 12 (31,749,391 to 31,755,316, forward strand). Ensembl gene ENSG00000300510.
Gene Ontology:
Biological process: defense response to virus; host-mediated suppression of symbiont invasion; negative regulation of viral genome replication; response to interferon-alpha; response to interferon-beta; response to type II interferon; type I interferon-mediated signaling pathway
Cellular component: plasma membrane; membrane
Homologues: Orthologues: chimpanzee IFITM3 (77% identical), mouse Ifitm2 (62% identical), mouse Ifitm3 (62% identical), rat Ifitm3-ps2 (57% identical), mouse Ifitm7 (50% identical), rat Ifitm1 (50% identical), mouse Ifitm1 (48% identical). Paralogues in human: IFITM3 (93% identical), IFITM2 (89% identical), IFITM1 (62% identical), IFITM10 (32% identical), IFITM5 (27% identical).